EGFR (epidermal growth factor receptor)
Diseases named in the same sentence as EGFR in open-access papers (continued):
Sharing a sentence is not in itself a finding about the gene and the disease.
tumor (continued). "They found that CLTX-CAR T binds to 80% or more of tumor cells in 13/15 patient tumor samples, with the other two displaying 40% binding, regardless of HER2, IL13Ra2, or EGFR expression levels." (PMID 37754534, 2023). "The lack of a significant correlation between EGFR, VEGF, and MVC with tumor size suggests that neither these proteins nor angiogenesis are primarily involved in tumor growth." (PMID 37194849, 2023). "The single shortest distance per nucleus between an EGFR locus and a large RPB1 locus was not significantly different across NSC and tumour lines." (PMID 36476408, 2022). "The CD8 transmembrane region has also been used to generate chimeric antigen receptor (CAR)-expressing EVs that target either EGFR or HER2; the CAR-EVs promoted tumor regression and did not elicit significant toxicity." (PMID 36591444, 2022). "Patient characteristics were well-defined, with known negative status for EGFR and ALK genomic alterations of nonsquamous tumors and no missing data for tumor PD-L1 expression or patients’ performance status." (PMID 35205788, 2022). "Because of this, EGFR expression is not routinely tested for in the clinical setting for OSCC despite its established role in tumor aggressiveness." (PMID 35957892, 2022). "Therefore, sustained activation of EGFR signalling in non-malignant cells in the tumour microenvironment might influence the behaviour of transformed cells and can play an important role in tumour progression." (PMID 35681586, 2022). "We presume that this patient, unlike other patients with strong pEGFR tumor proficiency but with low OAPS gefitinib scores (e.g., patients 13 and 16, for instance) would very likely be a strong responder towards EGFR targeting." (PMID 36494469, 2022). "Lacking an EGFR-TKI, it was unsurprising that treatment with darifenacin alone had minimal effects on tumor growth." (PMID 36048538, 2022). "Fluorescence in situ hybridization (FISH) detection showed that tumor cells were intact on chromosomes 1p and 19q, CDKN2A nondeletion, and EGFR nonamplification." (PMID 35663322, 2022). "Abnormal EGFR activation is a well-known signal that stimulates EMT15–17 and can be initiated by the release of large amounts of EGFR ligands from tumor cells or nontumor cells in the tumor microenvironment." (PMID 36352257, 2022). "Another invasive tumor cluster is silent TPITenrich, which consists of the non-hormone secreting TPIT lineage, and is characterized by EGFR T693 phosphorylation in our datasets." (PMID 36307579, 2022). "Referring to the TCGA HNSC tumor dataset, we found a positive correlation between IFN-γ-related genes (IFN-γ, CD8A, and STAT1) and PD-L1 (CD274), but not between EGF-related genes (EGFR, AKT1, and MAP2K7), which seems to support the results of this study." (PMID 35456895, 2022). "Based on the non-inflamed phenotype of EGFR-driven non-small cell lung cancer (NSCLC), we found that targeting PKCδ is a promising strategy to induce tumor infiltrating lymphocytes (TIL)." (PMID 36482371, 2022). "At the same time, immunohistochemistry in tumor 2 showed that these malignant cells were positive for ER and GATA binding protein 3 (GATA-3) but negative for epidermal growth factor receptor (EGFR) and cytokeratin 5/6 (CK5/6)." (PMID 36578949, 2022). "The EGFR CAR T cell-treated tumors had the highest T cell infiltration with a negligible difference between week 1 and 2, while BDCA-2 CAR T cell treated tumor revealed the lowest T cell infiltration, regardless of the time point." (PMID 35836798, 2022). "Unlike EGFR hotspot testing, a complete exonic analysis of the EGFR gene by the NGS of tumor-derived materials (ctDNA or tissue) can facilitate a thorough assessment of EGFR mutations to guide patients toward the most appropriate treatment." (PMID 35323374, 2022).
tumor (continued). "Very recently, FDA approved tremelimumab in combination with durvalumab and platinum-based chemotherapy for patients with metastatic NSCLC with no sensitizing EGFR, ALK genomic tumor aberrations." (PMID 36551630, 2022). "Eligible patients had recorded programmed death-ligand 1 (PD-L1) tumor proportion score (TPS) and no known actionable EGFR/ALK/ROS1/BRAF genomic alteration." (PMID 35740512, 2022). "Finally, the evaluation of methylation in ctDNA via ddPCR, such as the detection of RASSF1A or paraoxonase 3 (PON3), may suggest the state of the disease and survival outcomes in CM patients, even in the absence of tumor mutation data for BRAF, RAS or EGFR genes." (PMID 35887633, 2022). "Nivolumab plus ipilimumab combined with chemotherapy (2 cycles) have been approved as first-line treatment for patients with metastatic or recurrent NSCLC, with no EGFR, or ALK genomic tumor aberrations in many countries." (PMID 36059606, 2022). "IL-1α-loaded polyanhydride nanoparticles did not affect the anti-tumor efficacy of cetuximab and their combination with cetuximab induced a T cell-dependent anti-tumor immune response and may represent a novel immunotherapeutic strategy for EGFR-positive HNSCCs." (PMID 36338731, 2022). "As an alternative to full-size antibodies, we have previously investigated the smaller, IR700-labelled EGFR-specific affibody molecule (ZEGFR:03115-IR700), aiming for more effective tumour penetration, faster delivery, and clearance from non-targeted tissues." (PMID 35057796, 2022). "The E/NSCLC patients, one with 3.4% EGFR+ and 10.5% CXCR4+ serum sEVs and the other with 4.1% EGFR+ and 12.6% CXCR4+ serum sEVs, both had nearly negative EGFR staining and low CXCR4 staining in the primary tumor tissue." (PMID 35269297, 2022). "This study aimed to retrospectively analyze patients with advanced EGFR-mutant NSCLC from a Taiwanese tertiary center and receiving EGFR-TKI treatment with or without tumor resection." (PMID 36581631, 2022). "Independent of the EGFR signalling, the second parallel “eHsp90α > LRP-1 autocrine loop” to promote tumour cell migration has been clearly established by previous studies." (PMID 35835845, 2022). "A strong association between SF3B1 expression and key tumor -markers of development/progression (VEGFA/MKI67/EGFR/CDK4/PDGFRA) was found in GBM (CGGA- and Rembrandt-datasets), but not in the non-tumor samples (Rembrandt-dataset)." (PMID 35086552, 2022). "In this study, we observed the downregulation of phosphorylated EGFR and its ERK1/2 and AKT downstream signalling pathways with no alternations of their total protein levels in tumours following krill oil supplementation in vivo." (PMID 35120511, 2022). "Moreover, STAT3 downstream of EGFR signaling pathway could promote the transcription of UTX, suggesting an “EGFR-STAT3-UTX” axis that participates in the progression of NSCLC, and can at least partly explain the higher levels of UTX in NSCLC tumor tissues comparing to normal samples." (PMID 34661759, 2022). "Small-molecule PROTACs for EGFR are demonstrated to decline IDO1 as well as PD-L1 in non-small cell lung cancer (NSCLC) cell lines and tumor tissues." (PMID 36080223, 2022). "Comparisons of PFS and OS between total patients receiving EGFR-TKI treatment with and without tumor resection were made." (PMID 36581631, 2022). "To assess the efficacy of EGFR-targeted therapies in EGFR-amplified OSCC, we generated two patient tumor-derived primary cell lines (PDCLs), one harboring EGFR-amplification (TKCC-OSCC-16) and one without EGFR-amplification (TKCC-OSCC-22)." (PMID 34912708, 2021). "Here, we showed that anti-EGFR nimotuzumab (domain III) did not alter the in vitro binding and tumor uptake in vivo of anti-EGFR 89Zr-8709-scFv-Fc." (PMID 33535661, 2021).
tumor (continued). "There was no significant change in the expression of miR-182-5p in tumor tissues of mice treated with EVs + miR-182-5p inhibitor + si-CMTM7, while the expression of CMTM7 was reduced, and the EGFR and AKT phosphorylation levels were significantly increased." (PMID 34294040, 2021). "In contrast, patients with mesenchymal CMS4 mCRC have a significant survival benefit when anti-EGFR is added to FOLFIRI, whereas for patients with CMS2 tumours no such benefit was seen." (PMID 34253874, 2021). "It was found that SSTR-targeted PDT led to tumor vascular shutdown, while untargeted PDT or EGFR-targeted PDT failed to produce an adequate vascular response." (PMID 34203805, 2021). "Conversely, in EGFR/MET mice, osimertinib’s effect was mild and non-significant (60% of tumor cells in vehicle-treated and 48% in osimertinib-treated mice)." (PMID 34298655, 2021). "Pre-clinical studies, involving co-culture of tumor cells and peripheral blood mononuclear cells, show that combined EGFR-TKI and anti-PD-1 antibody therapies do not produce synergistic tumor cell killing effects." (PMID 34178613, 2021). "The PaSSS-based combination for EGFR+ MDA-MB-468 TNBC cell line, comprising of anti-EGFR, anti-ER and anti-MAPK inhibitors stopped the MDA-MB-468 tumor growth, but not the growth of another TNBC, MDA-MB-231 cells, the PaSSS of which did not include EGFR." (PMID 34638492, 2021). "The tumor stage and tumor/node/metastasis (TNM) statuses of the WT EGFR and MT EGFR groups did not significantly differ." (PMID 33802737, 2021). "Therefore, the detection of ctDNA EGFRm could reflect the accurate molecular status of the primary tumor, and the plasma EGFR test could be a useful screening tool for the diagnosis of NSCLC when tumor tissue is insufficient or tumor genotyping is not feasible." (PMID 33270375, 2021). "There are many tumor markers on HCC cells that have not been yet targeted, such as EGFR, FGFR, PDGFR, MUC1, and mesothelin." (PMID 34679012, 2021). "Interestingly, uptake of EGFR and HER2 immuno-PET tracers was also lower in tumors treated with combined MET/MEK inhibition, which also corresponded to decreased total levels of HER2, EGFR, and pHER2 in tumor digests, suggesting that treatment may also interfere with the MET-HER2 cross activation." (PMID 32646879, 2021). "Another study showed a correlation between the expression of PD-L1 and EGFR in ESCC, as well as a negative correlation between them on tumor cells or tumor-infiltrating immune cells in ESCC." (PMID 33859939, 2021). "In both the COIN and PICCOLO trials a benefit of the addition of anti-EGFR was seen only for PFS, but not for OS, with an exception for the right-sided CMS4 tumours which benefited from the addition of anti-EGFR to irinotecan in both PFS and OS." (PMID 34253874, 2021). "PCr/ATP ratio was significantly lower in tumor voxels than in contralateral control voxels in all groups except for MGMT methylated, EGFR not amplified group." (PMID 34298788, 2021). "Overall, these observations, along with the lack of correlation between the levels of CPAP and EGFR in OSCC cell lines, suggest that tumor associated inflammation drives cellular accumulation of CPAP which may not be functional in terms of impacting EGFR signaling, EMT and/or tumor suppression." (PMID 33889303, 2021). "For example, EGFR, IL-1, IL-6, JAK-STAT, Wnt, Notch, and ESR1 signalling pathways were all found to be consistently downregulated in HPV+ cases, but not in HPV- tumours." (PMID 34944837, 2021). "After weighing the evidence, experts recommended CT doublet plus anti-EGFR as 1L treatment for patients with RAS/BRAF WT mCRC, regardless of the primary tumor location, when cytoreduction is the goal." (PMID 34868987, 2021). "LAT015 had a sharp decrease in tumor volume due to surgery during LAT, but this did not result in a decreased mutant EGFR AF." (PMID 34283064, 2021).
tumor (continued). "Another limitation of our study is the fact that none of the patients included received anti-EGFR treatment throughout the duration of the study, precluding a direct comparison of the data from the PDX with the patient’s tumor progressing under treatment." (PMID 34271981, 2021). "In a different study, PSMA × CD28 and EGFR × CD28 BsAbs enhanced the antitumor efficacy of the PD-1 blockade in syngeneic and xenograft tumor models and did not induce systemic T cell activation." (PMID 34358141, 2021). "NCCN guidelines recommend using anti-EGFR agents for treating RAS wild-type and left-sided tumors, whereas ESMO guidelines do not consider tumor location." (PMID 34868987, 2021). "All groups had significantly higher Pi/ATP ratio in tumor voxels compared to contralateral side except for MGMT unmethylated, EGFR not amplified group." (PMID 34298788, 2021). "Similarly, EGFR amplifications were found to be exclusive to only one or two regions of the multiregional samples, suggesting that genetic information obtained from a single biopsy may not be representative of the entire tumor." (PMID 34202449, 2021). "administration) in EGFR-positive MDA-MB-231-derived tumors, but not in EGFR-negative tumors; (iii) durable tumor retention (at least 24 h) and (iv) no accumulation in healthy organs, i.e., lung and heart." (PMID 34294133, 2021). "miR-589-5p is a potential prognostic marker of HCC that regulates tumor cell growth by targeting MIG-6, although the study did not examine EGFR or the GR–MIG6 axis." (PMID 33806040, 2021). "In the LCP-EGFR siRNA+LCP Pyro PA without light group and LCP EGFR siRNA + PBS with light group, SCC4 and SAS tumor volumes were reduced by ~140% and ~150%, respectively, compared to the PBS group." (PMID 34575510, 2021). "Anti-EGFR gold nanorods provided significant enhancement in PAI signal in MDA-MB-231 tumour and axillary lymph node metastases relative to MCF-7 tumour and non-lymph node metastases." (PMID 32872399, 2020). "Noteworthy, the least responsive PDX tumor model, CVM-4663, displayed the lowest, non-detectable level of EGFR expression/activation." (PMID 32414394, 2020). "GBM is highly aggressive neoplasia with a dismal prognosis, and patients with EGFR-driven tumors that have absent PTEN do not respond to anti-EGFR therapy." (PMID 33087132, 2020). "Additional genetic testing revealed the patient was negative for EGFR, ALK fluorescence in situ hybridization, ROS1, BRAF, and PD-L1 22C3 IHC with Tumor Proportion Score (TPS) was less than 1%." (PMID 33101670, 2020). "In these specific contexts with EGFR mutant and long EGFR-TKI exposure, phosphorylated Mig-6 does not function as a tumor suppressor, but rather contributes to the survival of cancer cells." (PMID 32552717, 2020). "EGFR, VEGF-A and L1CAM were highly expressed in tumor-negative tissue, whereas αvβ6 showed heterogeneous expression in metastases." (PMID 32545676, 2020). "We have previously generated a genes signature induced by EGFR nuclear non-canonical activity, including two genes, TYMS and CCND1, upregulated by 5FU/CDDP chemotherapy in tumor cells." (PMID 33015030, 2020). "ER-localized immature and mature EGFR were not clearly resolved by SDS-PAGE, perhaps owing to contribution of the mouse EGFR signal derived from the mouse tumor stroma." (PMID 32161259, 2020). "The body weights of the mice were not affected by treatment with EGFR‐CAR‐1, EGFR‐CAR‐2, or Con‐CAR NK cells in both xenograft models, suggesting that the tumor sizes were not affected by the health condition of the mice." (PMID 32592435, 2020). "Twenty-seven cases without available FFPE blocks (consultation cases), and 20 cases with histologically inadequate quality and quantity of tissue and/or with no invasive tumor area after the sections for CK5/6 and EGFR stains were excluded from the series." (PMID 32364614, 2020).
tumor (continued). "For instance, LumP tumours are strongly characterised by increased FGFR3 transcriptional activity as opposed to basal/squamous (Ba/Sq) tumours, which employ EGFR mechanisms." (PMID 32374509, 2020). "Furthermore, the 30% rate of EGFR testing before subsequent therapy is consistent with previous estimates (30–48%) and emphasizes that, during the study period, a substantial proportion of patients initiated a subsequent therapy without updated information on the molecular profile of the tumor." (PMID 32345265, 2020). "SIAHON expression indicates EGFR/RAS/RAF/MEK/MAPK pathway activation and tumor progression, whereas a lack of SIAH expression, SIAHOFF, indicates EGFR/RAS/RAF/MEK/MAPK pathway inactivation and tumor regression post-NACT." (PMID 32846967, 2020). "Although both tumors were characterized by a similar level of EGFR expression (upper row), Pb-S02 IHZ signal was detected only in the FaDu xenograft and not in the H292 tumor tissue." (PMID 32246002, 2020). "Molecular analyses for all patients were negative for EGFR and ALK aberrations, one patient had a MET‐amplified tumor and two patients had high TMB." (PMID 32548905, 2020). "EGFR and HER2 were down regulated and up regulated respectively in tumor tissues in comparison with non-malignant bladder tissues." (PMID 32795296, 2020). "However, in cases where the mutations affect different tumor cells, a given type of TKI can only target corresponding tumor cells (eg, EGFR‐TKI can only target tumor cells with EGFR alterations), and other tumor cells (ie, not carrying the targeted mutation) may be able to proliferate rapidly." (PMID 31016879, 2019). "From these findings, additionally targeting the AXL appears to be a rational approach to overcome EGFR resistance, since HER2/HER3 signaling inhibition is not sufficient for complete tumor suppression." (PMID 30700700, 2019). "In support of these results, immunoblotting of tumour lysates demonstrated comparable EGFR and increased HER2 in castrated CWR22 tumours treated with lapatinib, but no change in intact mice." (PMID 31209328, 2019). "Under serum starvation conditions, EFGR was found induced in the ADC tumour cell line A549, whereas in the SSC cell line EGFR remained low no matter which metabolic condition was present." (PMID 30956278, 2019). "Here, we used i.t. injection of Erb-sumIL2 into EGFR negative B16-SIY and MC38-OVA tumor to assess the change of antigen-specific T cell inside the tumor, but not for the targeting delivery of sumIL-2." (PMID 31462678, 2019). "First, xenografts of established human tumor cell lines may have different characteristics from those of primary human tumors, and thereby EGFR expression levels determined here is not directly comparable to the EGFR-positivity criteria commonly used in clinical setting." (PMID 31651282, 2019). "We investigated the ADCC function of cultured non-B, non-T NK cells against the target tumor cells with various expression levels of HER-2 and/or EGFR." (PMID 31610784, 2019). "Overall, 28 out of 43 patients (65%) whose tumours lacked a genomic match to a clinical trial were eligible for investigational drugs as a result of TMP analysis (PTEN, EGFR, HER2, GPNMB, MSLN, TROP2, TOPO1 or TOP2A as emerging positive predictive markers)." (PMID 31537838, 2019). "The tumour that subsequently recurred (MGG70RR) showed diploid EGFR, suggesting inhibitor-mediated elimination of EGFR-amplified tumour cells and propagation of EGFR non-amplified cell subpopulations." (PMID 30644426, 2019). "ZEB1 also has a tumor suppressive role, independent of its ability to induce EMT, given that ZEB1 is able to induce EMT in both KRAS- and EGFR mutant cell lines." (PMID 31867044, 2019).